RNU4-24P (RNA, U4 small nuclear 24, pseudogene)
Gene: Small nuclear RNA gene on chromosome 12 (96,303,375 to 96,303,513, reverse strand). Ensembl gene ENSG00000201435.
Homologues: Orthologues: chimpanzee U4 (99% identical), macaque U4 (88% identical). Paralogues in human: RNU4-10P (71% identical), RNU4-49P (69% identical), RNU4-46P (68% identical), RNU4-15P (67% identical), RNU4-51P (67% identical), RNU4-43P (66% identical), RNU4-52P (66% identical), RNU4-17P (64% identical), RNU4-36P (64% identical), RNU4-28P (63% identical), RNU4-66P (63% identical), RNU4-90P (63% identical), and 80 more.